MAOA (monoamine oxidase A)
Diseases named in the same sentence as MAOA in open-access papers (continued):
Sharing a sentence is not in itself a finding about the gene and the disease.
Brunner syndrome (16 papers, 2014 to 2025). Monoamine oxidase-A deficiency is a very rare recessive X-linked biogenic amine metabolism disorder characterized clinically by mild intellectual deficit, impulsive aggressiveness, and sometimes violent behavior and presenting from childhood. "For instance, Brunner syndrome-characterized by impaired impulse control and borderline intellectual disability-results from mutations in the monoamine oxidase A (MAO-A) gene." (PMID 40385793, 2025). "MAOA mutations primarily cause Brunner syndrome, a disorder characterized by intellectual disability and aggressive behaviour associated with MAOA dysfunction." (PMID 41070359, 2025). "In 1993, aggressive phenotypes of the Brunner syndrome were found to be related to mutations in the MAOA gene, which led to a complete or partial loss of the MAOA enzyme activity." (PMID 38667528, 2024). "In men, MAOA genetic deficiency leads to Brunner syndrome, a condition characterized by overt aggression, antisocial conduct, and autism-related intellectual disabilities." (PMID 35215325, 2022). "It should be noted that, to date, all studies that have addressed Brunner syndrome have focused mainly on investigating changes in (plasma or urinary) metabolite levels caused by various mutations in the MAOA gene sequence." (PMID 36536002, 2022). "Defective MAOA is associated with Brunner syndrome and the norepinephrine neurotransmitter release cycle." (PMID 32616892, 2020). "Brunner syndrome is caused by a MAOA mutation that leads to a MAO‐A deficiency and therefore an excess of monoamine neurotransmitters." (PMID 31448578, 2019). "Brunner syndrome is a disorder characterized by intellectual disability and impulsive, aggressive behavior associated with deficient function of the monoamine oxidase A (MAO-A) enzyme." (PMID 36536002, 2022). "Notably, the same modifications in NR2B subunits were identified in a recent study on neurons from individuals affected by Brunner syndrome, the clinical condition characterized by MAOA nonsense deficiency." (PMID 35215325, 2022). "Similarly, mutations and deletion in the MAOA gene, as found in the Brunner Syndrome (BS), have recently been observed to induce autism symptoms." (PMID 30558545, 2018). "Norrie’s disease is characterized by mental retardation, autistic behavior, and motor hyperactivity, and is caused by an X-chromosomal deletion that includes MAOA, while Brunner’s syndrome includes violent and criminal behavior in the phenotype and is due to an MAOA stop mutation." (PMID 24669826, 2014). "In 1993, a non-sense mutation of the monoamine oxidase A gene (MAOA), which results in MAOA deficiency, was associated with a syndrome characterized by mild retardation, extreme reactive aggression, and violent and impulsive behaviour among males in a single Dutch kindred, the Brunner syndrome." (PMID 29881923, 2018). "Another prediction of the GP model addresses the Brunner Syndrome issue, the human closest equivalent to the MAOA-KO mouse." (PMID 30558545, 2018). "While MAOA KO mice exhibit alterations akin to those displayed by individuals with Brunner syndrome, this genetic condition is rare; thus, the present findings cannot yet be fully generalized to other forms of aggression associated with low-activity MAOA genetic variants or reduced enzyme activity." (PMID 35215325, 2022). "Likewise, male MAOA knockout (KO) mice exhibit a spectrum of behavioral alterations strikingly congruent with those observed in Brunner syndrome, including high aggression, socio-communicative deficits, and maladaptive and perseverative responses." (PMID 35215325, 2022). "If only acute during a short time-span, a xenobiotic intrusion may lead to epigenetic regulations of a restricted brain region, by contrast with the Brunner Syndrome genetic disease, in which the MAOA deficit concerns every cell of the body." (PMID 30558545, 2018).
heart failure (16 papers, 2011 to 2025). Inability of the heart to pump blood at an adequate rate to meet tissue metabolic requirements. "There are still open questions: Is MAOA upregulated before the transition of cardiac hypertrophy to heart failure?" (PMID 37371593, 2023). "Additionally, DRIFT identified monoamine oxidase A and cytochrome P-450 reductase, which play a potential role in cardiomyocyte damage and pathogenesis of heart failure, as potential targets of doxorubicin." (PMID 38125869, 2022). "Consequently, Tg-MAOA displayed progressive cardiomyocyte necrosis leading to premature death by heart failure at about 9 months of age." (PMID 28546851, 2017).
conduct disorder (15 papers, 2006 to 2022). A disorder diagnosed in childhood or adolescence age group characterized by aggressive behavior, deceitfulness, destruction of property or violation of rules that is persistent and repetitive, and within a one year period. "Several studies have reported that MAOA polymorphism moderates the association between the environment and EC-related behaviors among adolescent boys, including conduct disorder, delinquency, and aggression." (PMID 32132943, 2020). "A recent study has shown that adolescents with conduct disorders who carried low-activity MAOA variants exhibited relatively pronounced inactivation of the precuneus during an inhibitory task." (PMID 32132943, 2020). "In the case of G×E interactions involving MAOA alleles and predicting antisocial behavior and/or conduct disorder, effect sizes reported to date are small on average." (PMID 17534436, 2007). "Several studies have shown that when exposed to childhood maltreatment, individuals possessing the low-activity MAOA allele may confer an increased risk of conduct disorder." (PMID 32132943, 2020). "Behavioral studies suggest that low-activity MAOA allele carriers may be at a high risk of conduct disorder." (PMID 32132943, 2020). "In particular, authors observed that maltreated children who developed conduct disorder and antisocial personality disorder had a genotype that resulted in low levels of monoamine oxidase A (MAOA) expression." (PMID 34630181, 2021). "Our earlier population based analysis on this group of subjects revealed significant contribution of MAOA rs6323 and MAOB rs56220155 in ADHD associated conduct disorder as well as ODD." (PMID 28982350, 2017). "Their results showed that maltreated children with genotypes that conferred low levels of MAOA expression were more likely to develop conduct disorder, antisocial personality disorder and adult violent criminal behaviour than children possessing high activity variants of MAOA." (PMID 16887023, 2006). "A study evaluated the predictive effect of MAOA on the intelligence of children with ADHD, in which approximately 40% of the sample had comorbidities with conduct disorder and oppositional defiant disorder." (PMID 35720651, 2022). "Over the last decade, several candidate genes (i.e., MAOA, DRD4, DRD2, DAT1, 5-HTTLPR, and COMT) have been extensively studied as potential moderators of the detrimental effects of postnatal family adversity on child externalizing behaviors, such as aggression and conduct disorder." (PMID 26537239, 2015).
mood disorder (15 papers, 2009 to 2026). A cognitive disorder a disturbance in which the person's mood is hypothesized to be the main underlying feature. "Although inhibitors of MAOA are used clinically mainly for the treatment of mood disorders, MAOA suppression might also be neuroprotective." (PMID 39339333, 2024). "Along with anti-manic effects of lithium and the antidepressant effects of bright light, these findings suggest that perturbations of the circadian gene network at several levels may influence mood disorders, perhaps ultimately through regulation of MAOA and its modulation of dopamine transmission." (PMID 19166596, 2009).
autism (14 papers, 2009 to 2025). Persistent deficits in social interaction and communication and interaction as well as a markedly restricted repertoire of activity and interest as well as repetitive patterns of behavior. "In a case-control association study, male children carrying four tandem repeats in the promoter region of the MAOA gene were found to have a twofold higher risk of developing autism compared to those carrying the 3-repeat allele." (PMID 40305279, 2025). "MAOA genotype effects in FXS children were the same as those previously observed in idiopathic autism: the low activity MAOA promoter polymorphism allele was associated with increased gray and white matter volumes in all cerebral lobes." (PMID 24669826, 2014). "Rather, we find that the association of MAOA with brain structure in similar in children with either FXS or autism or both." (PMID 24669826, 2014). "We have previously investigated relationships between genes of the serotonin system, including monoamine oxidase A (MAOA), and the associated trait of brain morphology in children with autism." (PMID 24669826, 2014). "We have previously shown that a functional promoter polymorphism of the MAOA gene is associated with brain structure volumes in children with idiopathic autism." (PMID 24669826, 2014). "The MAOA promoter polymorphism is similarly associated with brain structure volumes in both idiopathic autism and FXS." (PMID 24669826, 2014). "This work aims to study the association between autism and MAOA uVNTR, MAOB rs1799836, and DRD2 TaqI A. Also the study analyzed genomic sequence variations of miR-431 and miR-21." (PMID 24453887, 2013). "This work studied the association of autism with genetic variations in neurotransmitter-related genes, including MAOA uVNTR, MAOB rs1799836, and DRD2 TaqI A in 53 autistic patients and 30 healthy individuals." (PMID 24453887, 2013). "The MAOA polymorphism has been also reported to have a modifying effect in the intelligence of children with autism through the intrauterine environment." (PMID 19949574, 2009). "Given the multifaceted other players than MAOA that are involved in the regulation of serotonin levels, potential compensatory effects are surveyed, which may underlie the autism heterogeneity." (PMID 33262691, 2020). "In case of epigenetic masking (i.e., X-inactivation in women) or genetic variant (low/medium COMT), the MAOA downregulation is silently transferred to the next offspring where it may occur in a different genetic context leading to overt autism (case 2 above)." (PMID 33262691, 2020). "Therefore, overt-autism would be:caused by the persistence of epigenetic regulations (MAOA-, COMT +) after the end of a prenatal monoaminergic disruption (excess MAOA)." (PMID 30558545, 2018). "We have previously shown that the monoamine oxidase A (MAOA) promoter polymorphism is associated with cerebral cortical volumes in children with autism, and we now sought to determine whether the association was also present in children with FXS." (PMID 24669826, 2014). "While association studies of MAOA variants in autism have produced uneven results, the gene has been associated with cognitive and emotional traits of relevance to the disorder, and the MAOA protein is the primary target for MAO inhibitors, an important class of psychiatric medication." (PMID 24669826, 2014). "In addition, an association of autism with several MAOA haplotypes was recently identified, thus suggesting the presence of a causable polymorphism in the haplotype block." (PMID 19949574, 2009). "The role of 5-HTTLPR and MAOA in other behavioural characteristics (autism symptomatology, ADHD characteristics, repetitive behaviour and mood disorders) has not been investigated in FXS." (PMID 32862204, 2021). "Abnormalities of the serotonin system have repeatedly been described in children with autism, and MAOA is centrally involved in synaptic processing of serotonin." (PMID 24669826, 2014).
autism (continued). "For example, in a sample of 119 males with ASD, autism severity in terms of aggression, fears, and rituals was modified by the mother's monoamine oxidase A (MAOA) genotype." (PMID 22934172, 2012). "In first place, the monoamine oxidase MAOA is the only enzyme which degrades 5-HT, and growing evidences from neurochemical, epidemiological and genetic studies support MAOA as one of the genes involved in autism." (PMID 30558545, 2018). "Severity of autism tends to be slightly affected by MAOA/B genotype." (PMID 24453887, 2013). "Previous study found consistent association between the “low activity” allele of MAOA and larger brain volumes for regions of the cortex in children with autism but not in controls." (PMID 24453887, 2013). "Likewise, MAOA KO mice exhibit abnormal phenotypes, including marked reactive aggression towards intruder conspecifics, maladaptive reactivity to environmental cues, and autism-related phenotypes." (PMID 35215325, 2022). "5-HTTLRP is associated with the presence of aggressiveness and ADHD in males only and MAOA is located on the X chromosome, whereas the Leu33 allele in ITGB3 has been suggested to have a dominant effect in males and a recessive effect in females, as far as it concerns association to autism." (PMID 19949574, 2009). "Through our examination, we find that the MAOA polymorphism produces the same effects on brain structure in three groups of affected children: those with idiopathic autism, those with FXS and autism, and those with FXS but no autism." (PMID 24669826, 2014). "Not systematically tested in connection with blood levels of 5-HT nor in SERT-oriented models of autism, MAOA and its enzymatic partners however deserve interest, in connection with other concerned agents, including SERT, 5-HT receptors, and TPH2 among a large family of neurotransmission regulators." (PMID 33262691, 2020). "Meanwhile, on the research front, a computational model of autism (Béroule, 2018) predicted that besides its classical anticonvulsant properties, VPA could serve as an autism-modifying drug for its capacity to promote the type A monoamine oxidase (MAOA) genetic expression." (PMID 33262691, 2020).
glioma (14 papers, 2016 to 2026). A benign or malignant brain and spinal cord tumor that arises from glial cells (astrocytes, oligodendrocytes, ependymal cells). "In this study, we investigated genetic and epigenetic variation in the MAOA and 5HITT genes and their associations with serotonin pathway metabolites in glioma tissue." (PMID 41152544, 2025). "Doing so would be important since an association between rs14551722 and male GBM (as well as a possible association between this disease and MAOA-LPR) would have at least three potentially significant implications for glioma research." (PMID 31556016, 2019). "In summary, the results of the present study need additional replication, and a larger sample size, but tentatively suggest the possibility that MAOA-genotype might be associated with glioma development in males." (PMID 31556016, 2019). "The present study represents an attempt to address these issues by using biobanked glioma tissue from 216 adult patients to investigate genetic and epigenetic regulation of serotonin metabolism focusing on the 5HTT and MAOA genes." (PMID 41152544, 2025). "Besides CA, zonisamide and resveratrol target MAOA and MOAB genes, which convert oxygen and water into hydrogen peroxide, thereby increasing intracellular hypoxia, with MAOA inhibition found to decrease glioma proliferation and angiogenesis." (PMID 38701414, 2024). "However, the direct impetus for performing the study was a recently published series of experiments demonstrating direct effects of the MAOA protein on central features of glioma development." (PMID 31556016, 2019). "From a theoretical point-of-view there are at least three possible mechanisms by which variation in the MAOA-gene may be relevant to the development of glioma." (PMID 31556016, 2019). "We analysed genetic and epigenetic variation in the Monoamine oxidase A (MAOA) and serotonin transporter (5HTT) genes using 232 biobanked glioma tissue samples from 216 adult patients." (PMID 41152544, 2025).
panic disorder (14 papers, 2016 to 2023). An anxiety disorder characterized by multiple unexpected panic attacks with persistent concern of recurring attacks. "Especially MAOA gene has been identified as a potential risk gene for panic disorder." (PMID 31435520, 2018). "Other studies found MAOA hypomethylation in female patients with panic disorder when compared to neurotypical counterparts." (PMID 34210361, 2021). "In panic disorder, hypomethylation of monoamine oxidase A (MAOA) and glutamate decarboxylases 1 (GAD1) genes have been evident in recent studies." (PMID 32499729, 2020). "Such pattern of MAOA gene hypomethylation in panic disorder is in concordance with that in anxiety disorder or depressive disorder." (PMID 31435520, 2018). "At baseline, MAOA hypomethylation was dominant on panic disorder patient group compared to healthy control group." (PMID 31435520, 2018). "Epigenetic signatures such as methylation of the monoamine oxidase A (MAOA) gene have been found to be altered in panic disorder (PD)." (PMID 27045843, 2016). "Moreover, monoamine oxidase A (MAOA) methylation levels are lower in patients with panic disorder vs. healthy controls, and only patients who respond to cognitive-behavioral therapy experience upregulation of MAOA." (PMID 30323739, 2018). "Monoamine oxidase A (MAOA) hypomethylation, taken together with negative life events, showed relation with panic disorder." (PMID 31435520, 2018).
cholangiocarcinoma (12 papers, 2014 to 2025). A carcinoma that arises from the intrahepatic biliary tree (intrahepatic cholangiocarcinoma) or from the junction, or adjacent to the junction, of the right and left hepatic ducts (hilar cholangiocarcinoma). "Hypermethylation of the MAOA promoter region was reported to contribute to its downregulation in cholangiocarcinomas and nasopharyngeal carcinoma." (PMID 41338163, 2025). "Previous studies reported that hypermethylation of the MAOA promoter contributes to its downregulation in cholangiocarcinomas and nasopharyngeal carcinoma, while treatment with the DNMT inhibitor, 5-Aza, restores its expression in both cancers." (PMID 41338163, 2025). "Furthermore, downregulation of MAOA due to hypermethylation was noted in cholangiocarcinomas, where MAOA overexpression was shown to inhibit tumor growth and invasion." (PMID 41338163, 2025). "Furthermore, in cholangiocarcinoma tissue, MAOA expression was downregulated through promoter hypermethylation." (PMID 38520217, 2024). "Notably, overexpression of MAOA demonstrated an inhibitory effect on cholangiocarcinoma growth and invasion." (PMID 38520217, 2024). "Similarly, the reduced expression of MAOA has been shown to promote an invasive phenotype in cholangiocarcinoma, hepatocellular carcinoma and breast cancer." (PMID 32273550, 2020). "Real-time PCR analysis showed an increased expression of TPH1 and decreased Monoamine Oxidase A (MAO-A) expression in human cholangiocarcinoma cell lines compared with nonmalignant cell lines." (PMID 33525332, 2021).
Cognitive impairment (12 papers, 2015 to 2025). Abnormal cognition is characterized by deficits in thinking, reasoning, or remembering. "In humans, deficits in brain MAOA levels lead to a higher predisposition to aggressiveness and antisocial personality, as well as perseverative behavioral patterns and mild cognitive deficits." (PMID 35215325, 2022). "In the diagram, yellow triangles denote the intersecting targets, demonstrating that caffeine potentially exerts its therapeutic effects on cognitive impairment through multiple targets, including A2AR and monoamine oxidase A (MAOA)." (PMID 39670604, 2024). "Three intersecting targets—ACE, MAOA, and ADORA1—were identified as potential targets for caffeine in treating cognitive impairment under high‐altitude conditions, consistent with previous research." (PMID 39670604, 2024).